ZNF431 (zinc finger protein 431)
Description:
Sequence-specific DNA binding transcriptional repressor. Represses target gene transcription by recruiting HDAC1 and HDAC2 histone deacetylases. Acts as a specific transcriptional repressor for PTCH1 during embryonic development. Required for osteoblast differentiation and sonic hedgehog/SHH signaling response. Binds to the consensus site 5'-GCGCCC-3' in the promoter of PTCH1 (By similarity).
Synonyms: KIAA1969; ZFP932
Tractability: PROTAC: ubiquitination databases record sites on it.
Gene: Protein-coding gene on chromosome 19 (21,142,005 to 21,196,053, forward strand). Ensembl gene ENSG00000196705.
Subcellular location: Nucleus
Pathways (Reactome):
Gene expression (Transcription): Generic Transcription Pathway
Gene Ontology:
Molecular function: chromatin binding; DNA-binding transcription factor activity, RNA polymerase II-specific; RNA polymerase II cis-regulatory region sequence-specific DNA binding
Biological process: negative regulation of transcription by RNA polymerase II; regulation of DNA-templated transcription
Cellular component: nucleus
Genetic constraint (gnomAD): Loss-of-function variants: 33 observed, 52.99 expected, observed/expected ratio (o/e) 0.62, 90% interval 0.47 to 0.83. The upper end of that interval is the gene's LOEUF score, 0.83, which puts it in group 3 of 6, group 1 being the genes least tolerant of losing a copy. Missense variants: 583 observed, 652.27 expected, observed/expected ratio (o/e) 0.89, 90% interval 0.83 to 0.96. Synonymous variants: 202 observed, 218.89 expected, observed/expected ratio (o/e) 0.92, 90% interval 0.82 to 1.04.
Homologues: Orthologues: chimpanzee ZNF431 (99% identical). Paralogues in human: ZNF430 (78% identical), ZNF92 (69% identical), ZNF98 (66% identical), ZNF257 (64% identical), ZNF737 (64% identical), ZNF675 (63% identical), ZNF66 (63% identical), ZNF680 (62% identical), ZNF723 (61% identical), ZNF730 (61% identical), ZNF273 (60% identical), ZNF626 (60% identical), and 6 more.
Diseases named in the same sentence as ZNF431 in open-access papers:
ZNF431 is named in the same sentence as 1 disease in open-access papers, as found by Europe PMC text mining. Sharing a sentence is not in itself a finding about the gene and the disease. The quoted sentences say what the papers report.
breast tumors (1 paper, 2023). "In their analysis, the genomic region harboring ZNF714 (and other genes, including its closest neighbors: ZNF85, ZNF430, ZNF431, ZNF708) was found to undergo copy number gains in estrogen-negative (ER-) breast tumors as compared to ER+ tumors." (PMID 37958512, 2023).